IL17A (interleukin 17A)
Diseases named in the same sentence as IL17A in open-access papers (continued):
Sharing a sentence is not in itself a finding about the gene and the disease.
tuberculosis (continued). "A series of further experiments involving patients with active, latent, or cured tuberculosis (TB) was able to describe the role of IL-17A and Th17 responses in patients with active TB, when compared to those with latent TB." (PMID 39737182, 2024). "Thus, a baseline cytokine signature of TNFα, IL-2, and IL-17A could serve as an accurate biomarker for the diagnosis of pediatric tuberculosis." (PMID 33936077, 2021). "Therefore, if the subjects get tuberculosis disease, and considering they carry a genotype that induce their cells to produce higher levels of IL-17A, that may expose these individuals to a worse disease outcome." (PMID 28098168, 2017). "Six studies were included in a systematic review on the role of IL-17A in active and latent tuberculosis (TB), and three studies on the role of IL-17A in Bacillus Calmette-Guerin (BCG) vaccination." (PMID 28916742, 2017). "Moreover, we found that SNPs of rs3819024 in IL-17A and rs763780 in IL-17F might be weakly related to the tuberculosis prognosis." (PMID 27339100, 2016). "MAIT cells show therapeutic potential for tuberculosis due to their ability to recognize Mtb antigens and produce pro-inflammatory cytokines (e.g., IFN-γ, TNF-α, IL-17A), which enhance antimycobacterial immunity." (PMID 40825006, 2025). "A previous study by our group demonstrated that Advax-CpG formulated with a tuberculosis vaccine enhanced CD4+ IFN-γ and IL-17A responses after challenge, but the CpG component was dispensable for protective efficacy." (PMID 36411332, 2022). "Nevertheless, while the contribution of IL17A to mycobacteria immunity is usually accepted, the role of IL17F in tuberculosis disease has been poorly studied to date." (PMID 31616423, 2019). "The presence of autoantibodies targeting cytokines has been noted in various infectious diseases: anti-interferon-α antibodies in severe SARS-CoV-2 infection; anti-interferon-γ antibodies in tuberculosis and anti-IL17A/IL-17 F/IL-22 in chronic mucocutaneous candidiasis." (PMID 40123018, 2025). "Similarly, in a Chinese cohort of 306 patients treated with IL-17A inhibitors for psoriasis, 17 out of 220 initially IGRA-negative individuals became IGRA-positive, and one case of active tuberculosis was reported." (PMID 41574365, 2025). "In the HIV-1 infected outpatient control group without active tuberculosis, the number of nodal connections with IL-17A was significantly higher in those with lower CD4 cell counts and unsuppressed viral loads." (PMID 34386782, 2021). "Conversely, network analysis of the primary discovery cohort showed that tuberculosis infection in the absence of HIV-1 co-infection contributed little to IL-17A network connectivity, even in those with extensive tuberculosis disease on chest radiograph." (PMID 34386782, 2021). "Moreover, Mtb-Ag-stimulated PBMCs from TB carrying the C allele produced the lowest levels of IFNG, the highest level of IL17A, and the minimum proliferation indexes as compared to TT TB, suggesting a relationship between the C allele and tuberculosis severity." (PMID 31616423, 2019). "In order to get further evidences that support the protective role of the AA genotype in developing tuberculosis, we next stimulated PBMC from HD carrying the different genotypes of the rs2275913 SNP with Mtb-Ag, then IFN-γ and IL-17A production were determined by ELISA and Flow Cytometry." (PMID 28098168, 2017). "Given that IL-17 may therefore be important in TBM-IRIS pathogenesis, but considering the low concentrations previously found in vivo in patients with tuberculosis, we measured IL-17A with a high-sensitivity assay." (PMID 25107295, 2014). "In the monocytes of patients with severe tuberculosis, IL17A could not augment autophagy because of a defect in the MAPK1/3 signaling pathway." (PMID 38139387, 2023). "Our results indicate that IL17A and IL17F may have different roles in the context of tuberculosis." (PMID 31616423, 2019).
tuberculosis (continued). "However, we showed that treatment of mice harboring a chronic Mtb infection with 5-OP-RU was able to reduce bacterial loads ~10 fold in 3 weeks in a manner dependent on IL-17A,14 indicating that post-exposure stimulation of MAIT cells may be a promising host directed therapy for tuberculosis (TB)." (PMID 34158594, 2021). "Strikingly, and in sharp contrast with our reports studying IL17A production, we detected higher levels of IL17F in Mtb-Ag stimulated PBMCs from HD than in TB (p < 0.01), suggesting that these cytokines may play different roles during tuberculosis disease." (PMID 31616423, 2019). "Our findings indicate that increased IL-17A network connectivity is mediated by HIV-1 viraemia and not tuberculosis." (PMID 34386782, 2021). "Furthermore, we show that, while Secukinumab, an anti-IL-17A antibody, does not revert Mtb dormancy, the anti-IL-12-p40 antibody Ustekinumab and the recombinant IL-1RA Anakinra promote Mtb resuscitation, in line with the importance of these pathways in tuberculosis immunity." (PMID 32069329, 2020). "Thus, IP-10 and IL-17A are not suitable for bTB diagnosis, but IP-10 is considered a promising biomarker for human TB and can detect TB in children, HIV-positive patients, and those undergoing therapy for tuberculosis (10, 15, –, 17)." (PMID 31340991, 2019). "Induction of IL-2, IL-6, IL-10 (not shown), IL-17A, IFN-g and was higher in participants with BCG scars, but only IL-6 were induced more in participants with no past history of tuberculosis." (PMID 29680481, 2018). "However, there are studies that support that IL-17 and IL-22 may not be necessary for the prevention of TB; for instance, wild type mice administered anti-IL-17A antibodies, as well as both IL-17RA and IL-22 KO mice, are not more susceptible to M. tuberculosis infection than the respective controls." (PMID 33530627, 2021).
dermatitis (185 papers, 2012 to 2025). An inflammatory process affecting the skin. "IL-17 expression increases in acute lesions in AD skin compared to uninvolved skin in humans; mice studies showed that the deficiency of IL-17A mitigates the development of skin inflammation." (PMID 35883395, 2022). "In this study, we demonstrated that Nfkbiz-deficient (Nfkbiz−/−) mice with atopic-like dermatitis have elevated serum IgE Abs and drastically increased numbers of IL-17A-secreting CD4+ T cells in skin." (PMID 28740238, 2017). "In the present study, to assess the effectiveness of targeting IL-17A and IL-17F in treating systemic amyloidosis and arteriosclerosis, KCASP1Tg mice were cross-mated with IL-17A-, IL-17F-, and IL-17AF-deficient mice, and observed until late stage of dermatitis." (PMID 39519167, 2024). "Furthermore, we conducted IHC staining for IL-17A, a cytokine associated with Th17 cells, which also play a critical role in skin inflammation." (PMID 39201715, 2024). "Notably, it was shown that γδ T cells are a primary producer of IL-17a, a cytokine that plays a significant role in skin disorders, inducing a cascade of cytokine expression associated with a pro-inflammatory signature through IL-17a and IL-17f secretions." (PMID 39273201, 2024). "When these findings are considered together, CD103+ dDCs and IL-17A- and IL-22-secreting skin-resident T cells may be associated with skin inflammation in Nfkbiz−/− mice." (PMID 28740238, 2017). "Infusion of hGMSCs in mice improved skin inflammation by suppressing several pro-inflammatory cytokines related to Th-1 and Th-17, such as IL-1, IL-17A, IL-17F, IL-21 and IL-22, as well as TNF-α and IFN-γ." (PMID 40748586, 2025). "In this model, neutralizing IL-17A inhibited the development of dermatitis and ankylosing enthesitis." (PMID 39919800, 2025). "For instance, increased interleukin (IL)-17A in the gut leads to systemic IL-17, affecting skin inflammation." (PMID 40869018, 2025). "Together, in vivo data support that dual blockade of IL-17A and IL-36R had improved efficacy in suppressing skin inflammation." (PMID 39600699, 2024). "A study using a long-lasting dermatitis mouse model that overexpressed human caspase-1 in keratinocytes (Kcasp1Tg) investigated the effects of deleting IL-17A and IL-17F on visceral complications." (PMID 39519167, 2024). "Ferulic acid inhibits secretion of IL-17 and blocks the combination of IL-17A and IL-17RA, thus improving skin inflammation in psoriatic mice." (PMID 38975345, 2024). "Prior research indicates that the progression of visceral amyloidosis secondary to skin inflammation can be mitigated by inhibiting IL-17A during the early and mild phase of the disease, as well as through the application of JAK inhibitors." (PMID 39519167, 2024). "ZC3H12A/Regnase-1 has been previously shown to suppress imiquimod-elicited skin inflammation by regulating IL-17A and IL-17C responses." (PMID 38470486, 2024). "Despite less improvement in dermatitis, deletion of IL-17A in Kcasp1Tg mice showed promising results in reducing multiple organ amyloidosis." (PMID 39519167, 2024). "Rosmarinic acid can alleviate psoriasis-like dermatitis in mice by decreasing the differentiation of Th17 cells and inhibiting the expression of IL-17A." (PMID 38975345, 2024). "A recent study has found that mice fed a Western-style diet for a short period of time exhibited IL-17A-mediated skin inflammation before significant weight gain occurred." (PMID 38033573, 2023). "In the analyzed skin disorders, IL-17A+ cells were observed in similar amounts, with a median of 3 IL-17A+ cells in LP, 5.5 in PV, and 5 in BP." (PMID 37415985, 2023). "For example, IL-23 acts upstream of IL-17A and is an important driver of skin inflammation in the imiquimod model." (PMID 36477177, 2022). "AEC-SC attenuated skin inflammation through suppressing the infiltration of neutrophils and IL-17A-producing T cells and reducing the expression of inflammatory cytokines and chemokines." (PMID 35922852, 2022).
dermatitis (continued). "Compared with inflamed dermatitis mice, the contents of tnf-α, ifn-γ, il-2, and il-17a were significantly lower in mice that received isovitexin." (PMID 34456714, 2021). "When evaluated both clinically and histologically at day 7, treatment with anti-IL-17A antibody improved the dermatitis in both PD-1−/− and WT mice to a level equivalent to treatment with anti-IL-6R antibody." (PMID 33060784, 2020). "Aging CD4CreTTPf/f mice developed spontaneous skin inflammation and displayed an increase in systemic IL-17A and skin TH17 cells." (PMID 32922402, 2020). "Mice overexpressing IL-17A in keratinocytes (K14-IL-17Aind/+ mice) exhibit severe psoriasiform skin inflammation and vascular dysfunction in conjunction with infiltration of the vasculature by inflammatory myeloid cells." (PMID 32070069, 2020). "The role of IL-8, IL-17A and TNFα in skin inflammation has been widely described in previous studies." (PMID 33371334, 2020). "The increased IL-17A along with spontaneous dermatitis development in old CD4CreTTPf/f mice demonstrates a role for TTP in regulating T cell-mediated inflammation." (PMID 32922402, 2020). "WD intake for 4 weeks promotes mild dermatitis and accumulation of IL-17A-producing γδ T cells in the skin." (PMID 33292701, 2020). "IMQ treatment was shown to increase serum IL-17A as well as skin inflammation, which led to systemic immune activation." (PMID 28761880, 2017). "In this study, we showed that spontaneous dermatitis developed in Nfkbiz−/− mice along with expansion of IL-17A- and IL-22-secreting CD4+ T cells." (PMID 28740238, 2017). "Antibiotic treatment relieved the dermatitis in Nfkbiz−/− mice, accompanied by decreased numbers of IL-17A- and IL-22-secreting CD4+ T cells." (PMID 28740238, 2017). "IL-22 and IL-17A are also necessary for epidermal hyperplasia in this model, as dermatitis was greatly reduced in IL-22 KO or IL-17A KO mice." (PMID 22229105, 2012). "In the present study, we showed that epicutaneous immunization of mice with a combination of Ova and SEB exhibited significantly enhanced skin inflammation, particularly IL-17A than Ova-sensitization alone, suggesting that SEB contributes to Ova-induced AD." (PMID 22848348, 2012). "During skin inflammation, S. aureus epicutaneous exposure resulted in eosinophil infiltration where these cells had a comparable contribution to the skin inflammation as T cells, in an eosinophil-derived IL-17A and IL-17F dependent manner." (PMID 40005560, 2025). "However, the skin inflammation in AD is a mixture of many inflammatory cytokines, including IL-17A and IL-17F." (PMID 39519167, 2024). "All mice with oxazolone-induced dermatitis had a dramatic increase in IL-1β, IL-4, IL-6, IL-10, TNF-α, IFN-γ, IL-16, IL-17C, IL-17E, IL-17F, IL-21, IL-22, and MIP-3a, whereas the concentrations of IL-12p70, IL-2, IL-17A, and IL-23 were lower in dermatitis mice." (PMID 37889696, 2023). "Dermatitis improved and mRNA levels were partially ameliorated in Kcasp1Tg with IL-17A/F deletion." (PMID 36982506, 2023). "In addition, there was an increasing trend in type 3 cytokines such as IL-17A and IL-22, suggesting an effect of skin inflammation, tissue repair, and infection on the production of anti-microbial peptides." (PMID 38203647, 2023). "In imiquimod-induced dermatitis, IL-17A, IL-17F, and IL-22 may be mostly derived from Th17 cells or γδT17 cells, while CXCL1, CXCL2, CCL20, and IL-17C may be mainly produced by epidermal keratinocytes." (PMID 37762500, 2023). "In the present study, IL-17A+ cells were found in all three skin disorders to a similar extent." (PMID 37415985, 2023). "In addition to triggering skin inflammation, IL-17A stimulates the proliferation of keratinocytes, which also produce a variety of antimicrobial peptides and chemokines." (PMID 35372072, 2022). "As a result, increased accumulation of IL-17A producing γδ T cells in the lesions could lead to IL-17A-mediated dermatitis." (PMID 36341417, 2022).
dermatitis (continued). "We identified a critical role of proinflammatory cytokines such as TNF-α, IFN-γ, IL-2 and IL-17A in skin inflammation in this model and revealed that these cytokines may be regulated by SHP2 in vitro." (PMID 34456714, 2021). "However, when IMQ-induced, PS-like dermatitis was assessed in Ido2-deficient mice, skin erythema, scaling, thickness, and levels of TNF-α, IL-23p19, and IL-17A appeared increased." (PMID 34831399, 2021). "With newly generated T cell-specific TTP conditional knockout mice (CD4CreTTPf/f), we found that aging CD4CreTTPf/f mice displayed an increase of IL-17A in serum and spontaneously developed chronic skin inflammation along with increased effector TH17 cells in the affected skin." (PMID 32922402, 2020). "Therefore, keratinocyte-specific depletion of IκBζ is sufficient to completely suppress IL-17A–mediated skin inflammation in vivo." (PMID 31622280, 2019). "In addition, a study that used a repeated hapten application to induce AD in mice showed that IL-17A is necessary for the development of skin inflammation, IL-4 production, and IgG1 and IgE induction." (PMID 29259713, 2017). "Therefore, keratinocyte-derived IκBζ might not only be important for skin inflammation but also represent a critical regulator of the microbiome, thus explaining why IL-17A–producing γδ T cells expand in the skin of untreated K14-KO animals." (PMID 31622280, 2019). "Interestingly, IL-17A is detected in the AD-like dermatitis of flaky tail mice." (PMID 29259713, 2017). "In the context of the data, the increased levels of IFN-γ and IL-17A detected by us in the sera of patients may reflect a preferential induction and accumulation of Th17/Th1 cells in the foci of dermatitis or upper respiratory mucositis induced by S. aureus infection." (PMID 22639172, 2012). "Among several models developed for both dermatitis and ankylosing enthesitis, we selected male DBA/1J mice caged together, in which the symptoms were dependent on IL-17A and human PsA." (PMID 39919800, 2025). "In the context of skin inflammation, inflammatory cytokines such as TNF-α, IL-17A, and IL-22 induce keratinocytes to produce proinflammatory cytokines, including IL-1β, IL-6, TNF-α, and IL-23, which subsequently influence the liver to increase SAA production." (PMID 39519167, 2024). "The increases in TCF4 in these mice further validate the capacity for skin inflammation to regulate TCF4 expression, with KC data suggesting that TNF-α, IL-17A, and IL-17C likely contribute to regulating (decreasing) TCF4." (PMID 38470486, 2024). "Oral propionate decreased mRNA expression of IL-17A, IL-17C, IL-17F, IL-22, IL-6, IL-1β, TNF-α, CXCL1, and CCL20 in imiquimod-induced dermatitis in comparison between NDIS versus NDIP." (PMID 37762500, 2023). "In order to gain further insight into how CO ameliorates IMQ-induced skin inflammation, we examined the impact of CO on the expression of AIM2 inflammasome components in skin lesions and of serum IL-17A in the mice treated with IMQ." (PMID 36982727, 2023). "Oral propionate reduced inflammatory infiltrates and epidermal Ki67+ cells and reduced mRNA levels of IL-17A, IL-17F, IL-17C, IL-22, IL-1β, IL-6, TNF-α, CXCL1, CCL20 and increased those of TGF-β1and IL-10 in imiquimod-indued dermatitis." (PMID 37762500, 2023). "The HFD decreased mRNA expression of IL-17A, IL-17F, IL-22, TNF-α, IL-1β, CXCL1, CXCL2, and keratin 16, and increased mRNA expression of TGF-β1 and CDKN1A in imiquimod-induced dermatitis." (PMID 37762500, 2023). "Oral propionate and the HFD reduced mRNA expression of IL-17A, IL-17C, IL-17F, IL-22, IL-1β, IL-6, TNF-α, CXCL1, CXCL2, and CCL20 in imiquimod-induced dermatitis." (PMID 37762500, 2023). "The dog with peritonitis exhibited increased intracytoplasmic levels of IL-6, IL-12, IL-17A and TGF-β, whereas the dog with dermatitis presented increased expressions of IL-1α, IL-12 and TGF-β in lymphocytes." (PMID 26362860, 2015).